HNF4A (hepatocyte nuclear factor 4 alpha)
Diseases named in the same sentence as HNF4A in open-access papers (continued):
Sharing a sentence is not in itself a finding about the gene and the disease.
mucinous adenocarcinoma (continued). "HNF4α and PDX1 are transcription factors that regulate gastrointestinal differentiation and are expressed in human invasive mucinous adenocarcinoma and mouse models of this disease." (PMID 30475207, 2018). "HNF4α-positive non-mucinous adenocarcinomas included TRU-type and non-TRU-type cases; the latter tended to exhibit the high-grade phenotype with frequent loss of SMARCA4, and A549 was a representative cell line." (PMID 38710944, 2025). "In the field of lung adenocarcinoma, HNF4α was first reported as a characteristic marker for invasive mucinous adenocarcinomas (IMA), which were regarded as non-TRU-type lung adenocarcinomas." (PMID 38710944, 2025). "The remaining half of the HNF4α-positive non-mucinous adenocarcinomas were totally TTF-1-negative (8/8, 100%) and never harbored EGFR mutations (0/8, 0%), suggesting that they were the non-TRU-type lung adenocarcinomas." (PMID 38710944, 2025). "Although mucinous adenocarcinomas were detected in lung sections from KL mice, these KRASG12C/LKB1Null tumor cells retained expression of NKX2.1, and some cells also expressed the gastrointestinal transcription factor HNF4α." (PMID 39213022, 2024). "In contrast to the AdSCCs that arise stochastically from mucinous adenocarcinomas, these SCCs appeared to be discrete lesions and were not surrounded by HNF4α-positive mucinous adenocarcinoma." (PMID 30475207, 2018). "We propose that A549 is not a mucinous adenocarcinoma cell line, but A549 may be a representative cell line of HNF4α-positive grade 3 lung adenocarcinomas with aggressive pathological features." (PMID 38710944, 2025). "In addition, all cases in the variant group retained SMARCA4 expression, but in the non-mucinous group, loss of SMARCA4 was detected in 3 of the 15 cases (20%), much more frequently than in HNF4α-negative non-mucinous adenocarcinomas (3/208, 1.4%)." (PMID 38710944, 2025). "Herein, we found that HNF4α-positive non-mucinous adenocarcinomas frequently showed loss of SMARCA4 (3/15, 20%), much more frequently than in mucinous, enteric, and colloid adenocarcinomas (0/18, 0%), and HNF4α-negative non-mucinous adenocarcinomas (3/208, 1.4%)." (PMID 38710944, 2025). "In addition, some conventional non-mucinous adenocarcinomas are HNF4α-positive, which include not only TRU-type adenocarcinomas that are double-positive for TTF-1 and HNF4α but also non-TRU-type poorly differentiated (grade 3) adenocarcinomas with frequent loss of SMARCA4 expression." (PMID 38710944, 2025). "Interestingly, HNF4α-expressing KRASG12C/LKB1Null-driven lung tumor cells retained expression of NKX2.1, suggesting that NKX2.1 silencing is not required for the emergence of mucinous adenocarcinomas when LKB1 expression is silenced." (PMID 39213022, 2024).
hepatoblastoma (8 papers, 2011 to 2025). Hepatoblastoma (HB) is a malignant hepatic tumor and is the most common pediatric liver cancer. "The major liver regulatory proteins HNF4α and HNF1α were detected only in cultured HH and in both HepG2 and C3A hepatoblastoma cells." (PMID 40963742, 2025). "Accordingly, these results suggest that the differential methylation of HNF4A/CEBPA-binding regions can be responsible for the diversity in tumor differentiation in hepatoblastoma." (PMID 32656360, 2020). "In both cell lines the distal PAS generating the long 3′UTR (1–3180) was used frequently, representing about 75% and 60% of the HNF4A transcripts in the hepatoblastoma and kidney cell line, respectively." (PMID 22140441, 2011). "Although the relationship between β-catenin and HNF4A in hepatoblastoma remains to be elucidated, a similar mechanism could be at play here." (PMID 39567475, 2024). "In contrast, YAPS127A/β-catenin-induced hepatoblastoma were characterized by weak CK19 positivity and prominent nuclear HNF4α." (PMID 37381005, 2023). "In summary, based on the staining pattern for HNF4A and LEF1, we were able to unequivocally distinguish these two hepatoblastoma subtypes, while it was not evident with β-catenin staining alone." (PMID 39567475, 2024).
hyperinsulinemic hypoglycemia (8 papers, 2010 to 2024). An inherited autosomal recessive syndrome characterized by the disorganized formation of new islets in the pancreas and congenital hyperinsulinism. "Remarkably, the mutations p.R63W and LRG_483t1:c.427-1G > A in the HNF4α gene cause hyperinsulinemic hypoglycemia associated to hepatomegaly and renal Fanconi syndrome." (PMID 35725468, 2022). "In conclusion, in a case of clinically diagnosed FS with a history of neonatal hyperinsulinemic hypoglycemia, the p.R63W mutation in HNF4A should be suspected." (PMID 30005691, 2018). "In these reported case series, 100% (14/14) of the patients with HNF4A p.R63W mutations had infantile hyperinsulinemic hypoglycemia and 50% (7/14) were macrosomic." (PMID 30005691, 2018). "Inactivating mutations in HNF4a have been shown to cause hyperinsulinemic hypoglycemia during the fetal and newborn period, as well as MODY diabetes in adolescence." (PMID 20361036, 2010). "The HNF4A M125I mutation has also been identified as the cause of hyperinsulinemic hypoglycemia." (PMID 29899848, 2018). "Some variants, however, result in a biphasic phenotype manifesting with neonatal hyperinsulinemic hypoglycemia (HH) and HNF4A-MODY later in life." (PMID 38433330, 2024).
acute liver failure (7 papers, 2012 to 2024). Rapid deterioration of liver function causing encephalopathy and coagulopathy. "Meanwhile activin-HNF4α-coagulation axis plays a crucial role in determining clinical outcomes of severe acute liver failure." (PMID 39497124, 2024). "Kong and colleagues demonstrated the therapeutic effects of co-encapsulating hepatocytes with HNF4α-overexpressing human umbilical cord MSCs (HNF4α-UMSCs) in models of acute liver failure." (PMID 38694507, 2024). "Prospective studies are warranted to corroborate the relationship between HNF4α and transferrin levels in several forms of liver failure, i.e., acute liver failure, acute-on-chronic liver failure, and AH." (PMID 33593348, 2021). "Recently, we inhibited the expression of HNF4α in mice with acute liver failure induced by lipopolysaccharide and D-Galactosamine, and we found that the liver damage of mice with LF was alleviated and mortality rate was significant decreased (unpublished data)." (PMID 22257755, 2012).
cholangiocarcinoma (7 papers, 2016 to 2025). A carcinoma that arises from the intrahepatic biliary tree (intrahepatic cholangiocarcinoma) or from the junction, or adjacent to the junction, of the right and left hepatic ducts (hilar cholangiocarcinoma). "In contrast, diagnosis-associated proteins include several transcription factors, including HNF4A and PRDM1, which were previously associated with cholangiocarcinoma." (PMID 40470116, 2025). "In line with HNF4A’s role in controlling identity of additional endodermal organs, diminished HNF4A expression is likewise found in renal cancers and cholangiocarcinoma." (PMID 32998360, 2020). "Moreover, MuCCA1 and mIC-23 subcutaneous tumors from C57BL/6 mice displayed intense desmoplastic reaction and typical immunohistopathological features of cholangiocarcinoma, as evidenced by CK19 and a-SMA positivity and HNF4α negativity." (PMID 38926350, 2024). "Compared to the other cancer types, ATAC-seq samples of the DIAD and kidney carcinoma classes as well as those of the liver-associated cancer types, including liver hepatocellular carcinoma (LIHC) and cholangiocarcinoma (CHOL), showed clearly higher HNF4A activity scores." (PMID 35227282, 2022). "Conversely, ectopically expressing HNF4α in human cholangiocarcinoma QBC939 cells, which have extremely low endogenous HNF4α but derived from the same embryonic origin with liver, resulted in a significant increase in the protein and mRNA expression levels of Exo70." (PMID 26848864, 2016).
cholestasis (7 papers, 2018 to 2024). Impairment of the bile flow caused by obstruction within the liver, or outside the liver in the bile duct system. "In the mouse PNAC model, antagonism of HNF4a decreased NFκB binding to the Abcb11 promoter, normalized Abcb11 expression and attenuated cholestasis." (PMID 37173326, 2023). "This downregulation is typically controlled by transcription factors, such as HNF4α, under cholestasis conditions." (PMID 29805766, 2018). "Taken together, these data suggest that targeting hepatic NFκB through antagonism of HNF4α may be an effective approach to reverse cholestasis and hepatocellular injury in PNAC." (PMID 37173326, 2023). "Additionally, HNF4A has been linked to elevated levels of gamma-glutamyl transferase (GGT), a sensitive marker of cholestasis." (PMID 38356679, 2023). "CSA, a well-known inducer of cholestasis, downregulated gene expression of CYP7A1, CYP27A1, BAAT, HNF4A, and INSIG1, while it upregulated ACAT2 and CCL20 gene expression." (PMID 38953992, 2024). "Thus, treatment with the HNF4α antagonist BI6015 reversed the evidence of hepatocyte injury and cholestasis during murine PNAC." (PMID 37173326, 2023). "Here we demonstrate upregulation of HNF4α in PNAC and that pharmacologic antagonism of HNF4α (by BI6015) significantly reduced hepatic NFκB activation, induced hepatocyte bile and sterol transporter expression, and reduced cholestasis and hepatic injury in murine PNAC." (PMID 37173326, 2023).
Crohn disease (7 papers, 2013 to 2025). A gastrointestinal disorder characterized by chronic inflammation involving all layers of the intestinal wall, noncaseating granulomas affecting the intestinal wall and regional lymph nodes, and transmural fibrosis. "HNF4A is also known to affect inflammation and immune pathways in other immune-mediated conditions such as Crohn’s disease and inflammatory bowel syndrome." (PMID 33207582, 2020).
gastric adenocarcinoma (7 papers, 2017 to 2025). "Recent studies have shown that changes in HNF4α gene expression are associated with many types of cancers, such as hepatocellular carcinoma, renal cell carcinoma, gastric adenocarcinoma, small intestine carcinoma, and colorectal cancer." (PMID 30405404, 2018). "Consistent with the current results in gastric adenocarcinomas, gastric intestinal metaplasia and Barrett’s esophagus showed increased expression of HNF4α in conjunction with CDX2." (PMID 39768557, 2024). "HNF4α expression in intestinal-type gastric adenocarcinomas correlated with the expression of MUC2." (PMID 39768557, 2024). "Therefore, the aim of this study was to evaluate the capacity of a concise panel of known BC markers together with GCDFP-15 and HNF4A to accurately distinguish primary gastric adenocarcinoma from metastases to stomach in the Brazilian population." (PMID 28583188, 2017). "Moreover, our data confirmed HNF4A as a potential marker in primary gastric adenocarcinoma and suggest the utility of a four-marker immunohistochemistry panel." (PMID 28583188, 2017).
Hypertension (7 papers, 2011 to 2025). The presence of chronic increased pressure in the systemic arterial system. "As there are large individual differences in HNF4α expression amongst patients as recently reported by us, patients with low HNF4α activity might be at higher risk for developing cyclosporine induced hypertension." (PMID 21298017, 2011). "The identification of HNF4A as a commonly activated factor supports its potential as a therapeutic target in the overlapping molecular landscape of metabolomic and hypertension disorders." (PMID 40909129, 2025). "HNF4A mRNA expression was increased in the aorta of the hypercholesterolemia plus sham-operated group- and hypertension plus hypercholesterolemia group (3.64 and 2.25-fold change respectively), compared to controls on a normal diet." (PMID 23874591, 2013). "Immunostaining of the aorta with HNF4A antibody showed that the endothelial layer of hypercholesterolemia plus sham group and the hypertension plus hypercholesterolemia group were densely stained for HNF4A, compared to controls." (PMID 23874591, 2013). "Here, we studied the effect of cyclosporine on HNF4α and various RAS components to better understand cyclosporine induced hypertension and proposed HNF4α dysfunction and subsequent regulation of AGTR1, ACE, and ACE2 as a molecular rational." (PMID 21298017, 2011). "The common area between the hypertension only- and hypercholesterolemia plus sham groups showed up-regulated focus genes related to UBC, APP, SERPINB2, TNF and HNF4A, and down-regulated focus genes related to UBC." (PMID 23874591, 2013).
liver failure (7 papers, 2012 to 2024). A liver disease characterized by the liver losing or has lost all of its function. "Another markedly up-regulated transcription factor, HNF-4α, has been previously shown to be expressed abundantly by peritoneal macrophages where it induced the expression of fibroleukin, a protein linked to the pathogenesis of hepatic failure." (PMID 22511950, 2012). "Hepatic HNF-4α-dependent gene expression is altered across the spectrum from fibrogenesis to decompensation and liver failure." (PMID 36652164, 2023). "In line with that, a forced re-expression of HNF4α rapidly reversed fatal liver failure in CCl4-treated rats." (PMID 33593348, 2021). "The findings from experimental data also indicated that the over-expression of HNF4α was an important factor for the occurrence of liver failure, which was consistent with the findings observed in liver tissue samples of patients with SHB in present study." (PMID 22257755, 2012). "Thus, transferrin constitutes both a prognostic and a mechanistic biomarker and an attractive surrogate for therapeutic trials aiming to preserve HNF4α signaling as a tool to prevent the development of liver failure." (PMID 33593348, 2021). "Consequently, they may serve as a surrogate of impaired hepatic HNF4α signaling and liver failure." (PMID 33593348, 2021).
lung carcinoma (7 papers, 2015 to 2022). "FOXA3 and SPDEF induce MUC5AC and MUC5B, while HNF4A induces MUC3 in human lung cancer cells harboring a KRAS mutation." (PMID 36860703, 2022). "Grhl2 is a key regulator of the E/M hybrid state of lung cancer cells, and Hnf4a is the master effector of mesenchymal-epithelial transition (MET) and is able to maintain hepatocyte identity." (PMID 29540203, 2018). "Activation of HNF4α in lung cancer leads to higher lung cancer grade and shorter survival." (PMID 36249028, 2022). "Since our data also revealed the activation of IL-6 inflammatory feedback loop via a STAT3-NF-κB pathway, we speculated that NF-κB may down-regulate miR-124 though repressing HNF4α expression in the metastatic lung cancer cells, needing further study." (PMID 25749519, 2015). "In addition, HNF4α recognizes the SNP site RS401681, which can interact with Telomerase Reverse Transcriptase (TERT) promoter to increase lung cancer risks." (PMID 36249028, 2022).
alcoholic hepatitis (6 papers, 2019 to 2025). Acute hepatitis resulting from ingestion of alcohol. "In line with that, a defective expression of HNF4α was suggested to drive hepatocellular failure in alcoholic hepatitis, whereas its forced re-expression reversed experimental ALF." (PMID 40242314, 2025). "TGFβ is a key upstream regulator in alcoholic hepatitis, inducing Hnf4a expression from the P2 promoter (instead of P1) in human hepatocytes." (PMID 39261648, 2024). "Defective HNF4α regulation has been recently described as a driver of hepatocellular failure in alcoholic hepatitis." (PMID 36552746, 2022). "Common changes in the methylation levels of FABP1, SGK2, and HNF4A from fibrosis to cancer were found in NAFLD, hepatitis virus, and alcoholic hepatitis." (PMID 35655171, 2022). "The overall findings indicate that the formation of DMR networks involving FABP1, SGK2, and HNF4A could cooperatively and/or synergistically affect fibrosis and carcinogenesis in advanced NAFLD and viral and alcoholic hepatitis." (PMID 35655171, 2022).
Barrett esophagus (6 papers, 2017 to 2024). Esophageal lesion lined with columnar metaplastic epithelium which is flat or villiform. "HNF4A therefore has the potential to promote a pivotal initiation event in Barrett's esophagus formation." (PMID 30962179, 2019). "In support of this, recent single-cell RNA-seq analysis of the esophageal epithelium revealed a population of esophageal submucosal gland cells that are transcriptionally similar to Barrett's esophagus and express HNF4A and GATA6." (PMID 30962179, 2019). "Together these data therefore indicate that the regulatory network involving HNF4A, GATA6, HNF1B, and FOXA transcription factors is already established in Barrett's metaplastic, is maintained in EAC cells, and HNF4A may initiate the development of Barrett's esophagus." (PMID 30962179, 2019). "Biopsy samples from cases of human Barrett's metaplasia were analysed for the presence of CDX2 and HNF4α." (PMID 27875772, 2017). "To further assess the potential role of HNF4A and GATA6 initiating Barrett's esophagus, we examined ATAC-seq signal from normal, Barrett's, and EAC tissue at genomic regions bound by HNF4A alone, GATA6 alone, and regions cobound by GATA6 and HNF4A." (PMID 30962179, 2019). "Using binding motif analysis within these DMRs, we show that a cell-type-specific transcription factor HNF4A maintains the binding sites that it generates in normal cells, while establishing new binding sites cooperatively with novel partners such as FOSL1 in esophageal adenocarcinoma." (PMID 37620896, 2023).
diabetic nephropathy (6 papers, 2015 to 2025). "GDC ameliorated the development of diabetic nephropathy by reduction of lipids accumulation in the kidney via SIRT1/AMPK/HNF4A pathway." (PMID 35480869, 2022). "Renal mRNA levels of transporters were reduced with diabetic nephropathy in females and the expression of transcription factors Hnf1β and Hnf4α in both sexes." (PMID 25710042, 2015). "The observed sex-dependent Hnf4α expression in obese ZSF1 rats was possibly induced by a higher degree of diabetic nephropathy in male animals as compared to females." (PMID 25710042, 2015). "HNF4α has been found to be suppressed in kidneys of patients with diabetic nephropathy as well as diabetic Zucker diabetic fatty (ZDF) rats, a model for diabetic nephropathy different from that used in this study." (PMID 25710042, 2015). "Immunohistochemical double staining for HNF4A and VIM of human kidney biopsies from pathophysiologically and temporally diverse kidney diseases, such as crescentic nephritis and diabetic nephropathy, displayed extensive increases in VIM expression combined with loss of HNF4A expression." (PMID 39954965, 2025). "Transient receptor potential canonical channel 1 (TRPC1), a target gene of HNF4α involved in mesangial cell contraction and glomerular function, is downregulated in patients with diabetic nephropathy, along with HNF4A expression, implicating this pathway in diabetic nephropathy pathogenesis." (PMID 41438090, 2025). "Our results proved the new role of HNF4A mediated by SIRT1 and AMPK signaling pathways in the lipid metabolism of diabetic nephropathy." (PMID 35480869, 2022). "Our network pharmacology results indicated that baicalin might improve diabetic nephropathy through SIRT1, HNF4A, JAK3, and HMGCR." (PMID 35480869, 2022). "However, the role of baicalin in diabetic nephropathy treatment and the regulation of SIRT1/AMPK/HNF4A pathway remains unclear and requires future studies." (PMID 35480869, 2022).